AKT3 (AKT serine/threonine kinase 3)
Diseases named in the same sentence as AKT3 in open-access papers (continued):
Sharing a sentence is not in itself a finding about the gene and the disease.
tumor (continued). "In addition to AKT3, AKT2 has also been found to have tumour suppressive functions in certain tissues as shown in two separate mouse models of breast cancer, where AKT2 deletion accelerated tumour development while AKT1 deletion inhibited tumour growth." (PMID 32453400, 2020). "Spheroid growth in vitro and tumor growth in vivo are suppressed in TNBC cells lacking AKT3 via upregulation of p27." (PMID 31752925, 2019). "Ablation of Akt1 in the TME generated an inhibitory effect on tumor size, without significant change in animal survival, while elimination of Akt2 or Akt3 resulted in increased tumor size, metastasis, and decreased survival time." (PMID 28929459, 2018). "A recent paper reported levels of Akt3 similar to Akt1 and2 in lung tumors, but found that ablating Akt3 did not change tumor growth compared to controls." (PMID 27533079, 2016). "Knocking down the Akt3 isoform moderately increased tumor size, metastasis and survival time compared to ID8 non-target and wild-type tumors." (PMID 27533079, 2016). "AKT3 exerts negative effects on tumor endothelial cell growth and migration by inhibiting the activation of translation regulatory kinase S6K." (PMID 25980492, 2015). "The histopathology between Jenv-induced tumors arising in WT, Akt1−/−, Akt2−/−, and Akt3−/− mice was similar suggesting that ablation of different isoforms does not result in the development of biologically distinct neoplasms." (PMID 24722238, 2014). "Other than in the Akt3 knockout mice, where 4 out of 20 mice exhibited extralobular tumor growth, the ablation of individual Akt isoforms did not appear to have an effect on local invasiveness or metastatic potential of Jenv-induced lung tumors." (PMID 24722238, 2014). "Ablation of Akt3 had a small, not statistically significant, stimulatory effect on tumor induction and growth by the viral oncogene." (PMID 24722238, 2014). "We observed an increase in FoxO3a phosphorylation in WT and Akt1−/− mice concomitant with tumor burden, but FoxO3a phosphorylation remained constant in Akt2 and Akt3 mice irrespective of tumor burden." (PMID 24722238, 2014). "In our cells, siRNA inhibition of AKT1/2 was partial and resulted in increased tumor cell survival, while suppression of AKT3 had no impact on tumor cell survival in the clonogenic assay." (PMID 22480225, 2012). "AKT3, a core member of the PI3K-AKT-mTOR pathway, can inhibit immune responses through multiple pathways: promoting the infiltration of regulatory T cells (Tregs), inhibiting the maturation of dendritic cells (DCs), and reducing the cytotoxicity of tumor-infiltrating lymphocytes." (PMID 41479783, 2025). "Mechanistically, transcriptomic profiling of LINC00960-depleted cells confirmed its tumor-promoting role, likely through sponging of hsa-miR-34a-5p, hsa-miR-16-5p, and hsa-miR-183-5p, leading to the upregulation of cancer-promoting genes including BMI1, KRAS, and AKT3." (PMID 39039064, 2024). "In contrast, AKT3 and MDM4 amplifications were the only driver CNV events found in RAI-refractory PTCs (both in 4.5%, 3/66 of cases; p = 0.076; Fisher’s Exact Test), and only a single RAI-avid tumor (PTC-501) exhibited multiple driver CNV events (p = 1.000; Fisher’s Exact Test)." (PMID 35326735, 2022). "Finally, AKT1 was upregulated in CLs, while AKT3 was downregulated across all sample groups except for basal-like TN tumours, while AKT antagonising factors such as PTEN were only downregulated in CLs and normal-like TN tumours." (PMID 36220861, 2022). "Furthermore, knockdown of AKT3 increased the activity and phosphorylation of pro-metastatic HER2 and DDR1/2 but lowered protein levels of CTGF after TGFβ-stimulation, an axis involved in tumor-induced osteolysis." (PMID 33670586, 2021).
tumor (continued). "Another interesting finding in our data is that tumors in the Amp signature cluster showed amplifications in AKT3 whereas tumors with the Del signature had amplifications in AKT2, suggesting that both tumor types may utilize the AKT survival pathway for tumorigenesis." (PMID 33800889, 2021). "Additionally, KEGG pathway enrichment analysis showed that AKT3 positive-related genes were significantly enriched in cancer-promoting signaling pathways such as ErbB and Hedgehog, suggesting that, in TGCT, AKT3 is more likely to promote tumor progression." (PMID 34882061, 2021). "Given the well-recognized tumor-promoting role of AKT3 we thus reckoned that miR-568 might function as an HCC suppressor in HCC via targeting degradation of AKT3." (PMID 33499874, 2021). "Furthermore, knockdown of AKT2 in the mice results in enhanced proliferative capacity and tumor growth, whereas ablation of AKT3 has a slight non-significant effect by attenuating tumor growth and induction." (PMID 31752925, 2019). "From these initial data, we cannot rule out the possibility that Akt2 or Akt3 may be more relevant in controlling the CSC phenotype in models from different tumour lineages." (PMID 29518912, 2018). "Similarly, knockdown of Akt1 and Akt3 significantly hampered cell proliferation in vitro and tumor growth in vivo, but Akt2 knockdown did not." (PMID 29090098, 2017). "Collectively, these data suggest that miR-497 may regulate proliferation, survival and tumor vascular permeability by targeting key genes involved in DDR such as WEE1 and CHEK1, cell growth and viability such as AKT3 and BCL2 and angiogenesis regulators such as VEGFA." (PMID 26824183, 2016). "However, tumor-free survival did not significantly differ among the kRas/Akt3, kRas/Akt3/Cdc20, and kRas/Akt3/c-Myc mice." (PMID 26993778, 2016). "This suggested that the sensitivity of CDH1-null cells to the pan AKT inhibitors may be explained more by the inhibition of AKT3 rather than AKT1 and AKT2, and therefore that over-expression of AKT3 represents a vulnerability in tumours deficient in E-cadherin." (PMID 35406381, 2022). "Moreover, in contrast to previous reports in HBC73–75, PIK3CA and other PI3Ks activating AKT as well as AKT1 and AKT3 were downregulated or not differentially expressed in tumours, suggesting that subtypes evaluated here are not likely to respond to therapies targeting PI3Ks and AKT inhibitors." (PMID 36220861, 2022). "However, because the PI3K/Akt pathway is one of the major survival pathways that is frequently upregulated in human tumors, Akt1 and Akt3 rather than DNA-PKcs are suggested to be tumor-specific targets as monotherapy as well as in combination with radiotherapy." (PMID 29090098, 2017). "Interestingly, neither Akt1−/− nor Akt3−/− mice had detectable levels of phosphorylated pGSK-3α/β (respectively) whereas Akt2−/− mice showed a decrease in pGSK-3α/β phosphorylation as tumor burden increased." (PMID 24722238, 2014). "Thus lack of Akt3 expression along with high level of endogenous huntingtin in CP70 cells may be the determinant factors of Trip10-induced tumor suppression." (PMID 21299869, 2011). "We next sought to test if AKT2 knockout impaired tumor initiation when compared to AKT1 and AKT3 deletion, as our CRISPR-edited WM1799 cells exhibited more robust AKT2 deletion compared to the inducible knockdown lines, which did not impact tumor initiation." (PMID 37894325, 2023). "Importantly, AKT3-174aa, but not circ-AKT3, could function as a tumor suppressor." (PMID 36142352, 2022). "It has been reported that AKT1 does not promote invasive phenotype, while AKT3 is required for TNBC proliferation and tumor growth." (PMID 34199634, 2021). "We observed a decrease in calcified bone volume after inoculation of 231-BO cells with AKT2 knockdown, AKT3 knockdown, and SCR control vector compared to NSG mice without tumor cell inoculation." (PMID 33670586, 2021).
tumor (continued). "Furthermore, this may not necessarily mean that AKT3 is not a target for tumor inhibition." (PMID 34384473, 2021). "Both the British and Indian tumor histology patterns revealed higher expression of AKT2 while expressions of AKT1 and AKT3 were not significant when observed in both liver and lung metastasized FPPE samples." (PMID 33227065, 2020). "Lastly, we found that only tumours E8 and E9 exhibited both elevated Akt3 expression and amplification of the Akt3 gene, whereas tumours E1, TB239-2 and TB242 hadelevated Akt3 expression but without Akt3 gene amplification." (PMID 28194015, 2017). "The expression of S100A4 in primary tumor samples was analyzed by Western blot analysis, showing a significantly increased overall expression of S100A4 in tumors lacking AKT3 compared to controls." (PMID 26741489, 2016). "Although AKT3 absence partially reproduces the effects induced by miR122 expression in BCLC9 cells, it is not enough to fully reduce tumor size." (PMID 27612430, 2016). "Moreover, although Akt3 is required for TNBC proliferation and tumor growth, it does not promote an invasive phenotype." (PMID 41471069, 2025). "Interestingly, in the comparison of CSP/CNSP groups, the genes AKT2, AKT3, and PTEN also exhibit a significant increase in expression in normal tissue but not in tumor tissue." (PMID 38505269, 2024). "Interestingly, this connects to a recently published work on Akt inhibitor resistance in castration-resistant prostate cancer (CRPC), where the authors also observed specific upregulation of Akt3, but not Akt1 or Akt2, in MK2206-resistance tumor cells." (PMID 36291790, 2022). "The number of lung tumors derived from FTO knockdown KYSE150 cells did not significantly change; however, AKT3-OE or sh-FTO & AKT3-OE significantly promoted the number of lung tumors compared with that in control cells, suggesting that AKT3 overexpression promoted tumor metastasis in vivo." (PMID 38491196, 2024). "Besides, AKT3 negative-related genes were found highly activated in metabolism-related signaling pathways such as the TCA cycle, oxidative phosphorylation, and glutathione metabolism, which suggested the involvement of AKT3 in the energy metabolism and oxidative stress of tumor cells." (PMID 34882061, 2021). "Interestingly, unlike the Akt1−/− and Akt3−/− mice, in which GSK-3 activity is high and does not appear to be inhibited in response to Jenv signaling, Akt2−/− mice possess a high level of basal GSK-3α/β phosphorylation which surprisingly decreases with increased tumor burden." (PMID 24722238, 2014).
cancer (183 papers, 2008 to 2025). A tumor composed of atypical neoplastic, often pleomorphic cells that invade other tissues. "RNA-seq analysis comparing parental and BTG3-KO HaCaT cells revealed elevated expression in BTG3-KO cells of several signature genes, such as fibronectin and AKT3, which have been implicated in cancer cell migration and metastasis." (PMID 38714880, 2024). "Although many miRNAs have been found to regulate the expression of AKT3 in cancer cells, much less is known regarding the underlying mechanisms of the miRNA/AKT3 axis in cancer progression, metastasis, and drug resistance." (PMID 37998329, 2023). "Nonetheless, results have revealed that AKT3 is dysregulated in a variety of cancers, and is associated with abnormal proliferation, apoptosis resistance, and the poor prognosis of tumors." (PMID 37998329, 2023). "Accordingly, we searched the literature via Google Scholar and PubMed and found novel information for networking the AKT1-, AKT2-, and AKT3-associated circRNAs and cell functions, especially for cancer cells." (PMID 36230902, 2022). "Serine/threonine kinase 3 (AKT3) is a protein-coding gene that is associated with several cattle immune diseases including different tumors and cancers." (PMID 34677734, 2021). "One thing these cancers of different origin have in common, aside from high AKT3 expression, is an association with mesenchymal features." (PMID 33673003, 2021). "Our results showed that high expression levels of AKT3 are associated with a better outcome and longer cancer-specific patients' survival rates in those patients who display the luminal A molecular class as well as in ER- and PR-positive ones." (PMID 31781306, 2019). "In NASH-HCCs, the 16 mutated genes involved in insulin signaling included insulin receptor (Insr) and some other well-known cancer-related genes (Mtor, Hras1, Akt3, etc), with Mtor and Hras1 recurrently mutated." (PMID 30367044, 2018). "It is important to note that E2F3 and AKT3 are both the predicted targets of miR-15, whose deletion was proved to be associated with cancer." (PMID 25821802, 2015). "A critical finding in the data presented here is the identification of two human cancer cell lines with the AKT3 E17K mutation." (PMID 18813315, 2008). "Hence, many miRNAs that directly bind the 3′-UTR of AKT3 and participate in the regulation of AKT signaling in human cancers have been revealed, and additional AKT3-associated ncRNAs are expected to be identified in the near future." (PMID 37998329, 2023). "Because the upregulated expression or activation of AKT3 is frequently observed in a wide variety of human cancers, and is associated with cancer progression and chemotherapy resistance, the specific targeting of AKT3 may be attractive in new drug discovery." (PMID 37998329, 2023). "Additionally, AKT3 was identified as the gene that is most strongly associated with all pathways and is involved in a variety of cancer-related processes." (PMID 36237545, 2022). "Furthermore, 16 mutated genes are involved in insulin signaling, such as insulin receptor (Insr), and some other well-known cancer-related genes (Mtor, Hras1, Akt3, among others), with Mtor and Hras1 commonly mutated." (PMID 36612019, 2022). "In this study, we found high level of circ_AKT3 might be associated with cisplatin resistance in GC, indicating the positive role of circ_AKT3 in GC, which was opposite to that in other cancers." (PMID 35233464, 2022). "Overexpression of PRKCQ and AKT3 are associated with invasive cancer phenotypes." (PMID 22546513, 2012). "Thus, this study represents the first report of an AKT3 mutation in human cancer." (PMID 18813315, 2008). "Girdin, an Akt phosphorylation enhancer, and Akt3 are involved in actin organization and cell motility, affecting cancer cell invasion, progression, and angiogenesis." (PMID 39801758, 2025).
cancer (continued). "We found that the overexpression of Akt3 and Mapk1 is a constant crossroad for inflammation, metabolic abnormalities, addictive behaviors, and cancer signaling pathways, suggesting a notable role." (PMID 39484291, 2024). "The biological term enrichment analysis of the mRNAs of this subnetwork revealed pathways associated with cancer, such as the enrichment of the GNAQ, STAT1 and AKT3 oncogenes in the MAPK signaling pathway." (PMID 38302900, 2024). "The upregulated eccDNAs enriched in the MAPK pathway in patients with poor survival outcomes originated from cancer-related genes, such as AKT3 and MAPK." (PMID 38903532, 2024). "Although Akt3 is the least expressed isoform, it is markedly regulated by K-Ras(V12) and is a crucial regulator of carcinoma cell-cell adhesion via modulation of E-cadherin and NCAM expression." (PMID 38291468, 2024). "In a specific type of human cancer, different dysregulated ncRNA/AKT3 axes are involved in tumorigenesis, progression, and drug resistance." (PMID 37998329, 2023). "For instance, the miR-145/AKT3 axis is found in several human cancers including BC, chemo-resistant BC, and PTC." (PMID 37998329, 2023). "By integrating the ncRNA profile and miRNA target prediction tools, links between ncRNAs and AKT3 can be established and validated in cancer cells." (PMID 37998329, 2023). "Given the interesting emerging roles of AKT3 in human cancers, important mechanistic insights regarding the AKT3 downstream effectors are expected to be discovered in the future." (PMID 37998329, 2023). "Numerous miRNAs directly target AKT3, whereas restoring their expression decreases AKT3 expression and exhibits therapeutic effects against a variety of cancers." (PMID 37998329, 2023). "Herein, we systemically summarize the tumorigenesis-related functions of AKT3 and the regulation of its expression by ncRNAs in specific cancer types." (PMID 37998329, 2023). "Many ncRNAs regulate the expression of AKT3, and consequently cancer development, progression, and chemosensitivity." (PMID 37998329, 2023). "The dearth of knowledge regarding AKT3 in cancer possibly stems from early reports that it is expressed predominantly in the brain, heart and kidneys, whereas AKT1 and AKT2 are expressed ubiquitously." (PMID 37292818, 2023). "Remarkably, recent studies have identified several circRNAs derived from the AKT3 gene and their involvement in the regulation of human cancers: hsa_circ_0017250, hsa_circ_0112784, hsa_circ_0112781, hsa_circ_0017252, and hsa_circ_0000199." (PMID 37998329, 2023). "The aberrant expression of AKT3 is found in many types of cancer, thus indicating an important role of this isoform in tumorigenesis." (PMID 37998329, 2023). "In contrast to the abundant evidence supporting the involvement of AKT in cancer induction and progression, relatively limited information is currently available regarding the specific role of AKT3 in oncogenesis." (PMID 37998329, 2023). "The aim of this review was to summarize current research progress in the isoform-specific functions of AKT3 in human cancers and the roles of dysregulated miRNA/AKT3 in specific types of human cancers." (PMID 37998329, 2023). "There is growing appreciation for AKT3’s role in cancer progression, and indeed, our data showed that knockdown of AKT3 decreased LNCaP invasiveness." (PMID 37292818, 2023). "Several mutated genes were identified in a murine NASH-associated HCC model, which has also been reported as drivers in other human cancers, including Mtor, Sdk1, Braf, Pik3cb, Ctnnd1, Ctnna3, Akt3, and Nos." (PMID 36612019, 2022). "We enrolled a total of twelve patients across eight different cancer types, including six patients with non-AKT1 E17K mutations (AKT1 D323G, E40K, L52R; AKT2 E17K, L78-Q79ins(HANTFVIRCL); AKT3 E17K) in this signal-seeking pilot study." (PMID 35440569, 2022). "A careful examination of more cell functions influenced by more AKT1-, AKT2-, and AKT3-targeting circRNAs on cancer cells is warranted." (PMID 36230902, 2022).